MYC (MYC proto-oncogene, bHLH transcription factor)
Diseases named in the same sentence as MYC in open-access papers (continued):
Sharing a sentence is not in itself a finding about the gene and the disease.
cancer (continued). "Both MYC and Twist1 demonstrated binding at multiple sites in the promoter regions of CCL2 and IL13 in the ChIP-seq data from several different cancer cell lines." (PMID 31933479, 2020). "Both MYC and TWIST1 are overexpressed in multiple human cancers, suggesting there is a common embryonic transcriptional program they regulate in the embryonic microenvironment which is hijacked by cancer cells." (PMID 31933479, 2020). "CDK7 has previously been reported to be a therapeutic target in cancers driven by MYC and THZ1 has consistently been shown to decrease the expression of MYC protein and mRNA." (PMID 32155786, 2020). "We then analyzed the gene amplification and mRNA upregulation of MYC in HNSCC (N = 279) as profiled by TCGA and queried on cBioPortal (HNSCC: Cancer Genome Atlas Network50, SCM: TCGA, PanCancer Atlas)." (PMID 32895364, 2020). "Other efforts focus on interrupting the dimerization of MYC with MAX, inhibiting MYC/MAX binding on the DNA, interfering with key c-MYC targets, and inhibiting c-MYC in cancer stem cells." (PMID 32737302, 2020). "Increases in MYC copy number and PVT1 expression occur in more than 98% of cancer cases with increased 8q24 copy numbers, indicating an interaction between PVT1 and MYC and suggesting that they are part of a common signaling pathway." (PMID 32992461, 2020). "The stem cell markers c-MYC and SOX2 play important roles in the regulation of differentiation and also regulate cancer cell growth and chemotherapy resistance." (PMID 33089188, 2020). "Related mechanism studies show that ribosome biosynthesis is an important part of Ras/Raf/MEK/ERK, MYC, and PI3K/Akt/mTOR pathways, which are proven to drive malignant tumors." (PMID 33584809, 2020). "Western blot assays showed that the decreased CDH1 expression and enhanced mesenchymal (CDH2 and vimentin) and cancer stemness (CD44, ABCG2, OCT4 and MYC) marker expression were abolished after treating MCF-7OE-UBE2O cells with rapamycin." (PMID 31907353, 2020). "Beside, c-MYC and other transcription factors, such as mTOR and HIF-1, can act synergistically to improve glycolysis and promote cancer proliferation." (PMID 33489906, 2020). "Here, we summarize the current knowledge on the interaction between MYC and UPR signaling, and its contribution to cancer development." (PMID 32310340, 2020). "It has also been suggested that the amplification and overexpression of MYC have been reported previously in both LSCC and hyperkalemia type carcinoma." (PMID 33092550, 2020). "The degradation of the MYC protein, combined with transcriptional downregulation of SYK, GCN5, and MYC, significantly reduces the cancer promoting properties of MYC." (PMID 31645904, 2019). "According to the description of the topology structure, the PVT1 promoter, MYC promoter, and the four enhancers belong to the same TAD in normal tissues, while in cancer cells, the circumstance is different." (PMID 31309249, 2019). "Recently, RuvB-like 2 (RUVBL2) was found to interact with catenin beta 1 (CTNNB1), telomerase reverse transcriptase (TERT), MYC proto-oncogene (MYC), nuclear factor-kappa B1 (NFKB1), etc. to regulate the cancer-related signaling pathways in HCC." (PMID 31572066, 2019). "The complex interactions of PVT1, its proximity to the MYC oncogene, and its upregulation in cancer has made PVT1 a gene of significant interest for both screening and therapeutic targeting of cancer." (PMID 31249809, 2019).
cancer (continued). "The cancer lines chosen as representative of EGFR and HER2-overexpression, MDA-MB-468 and BT474, respectively, also exhibit MYC amplification." (PMID 31839995, 2019). "Oncogene 5T4 is involved in the modulation of cell adhesion and is over-expressed in many types of cancer cells, as along with such oncogenes as MYC (proto-oncogene c-Myc) and NRAS (NRAS proto-oncogene, GTPase)." (PMID 31572192, 2019). "Our results showing an effect of lactate on expressions of MYC and HIF1A genes are consistent results of others showing an upregulation of the glycolytic pathway in cancer." (PMID 32010625, 2019). "Initial pharmacodynamics data analysis shows dose-dependent reduction of MYC, PCNA, and MCL-1 levels, all being relevant for cancer cell survival." (PMID 31253180, 2019). "We identified 156 focal amplifications and 69 focal deletions, in well-known oncogenes, such as ERBB2, CCNE1, KRAS, MYC, EGFR, and CDK6, and cancer-related genes such as GATA4, GATA6, CD44 and ZNF217." (PMID 31570735, 2019). "MYC upregulates the expression of immune checkpoints CD47 and PDCD1L1 on cancer cells by direct interaction with promoters of these two genes." (PMID 31824865, 2019). "The MYC family of transcription factors, including MYC, MYCN, and MYCL, are the most commonly altered oncogenes in cancer." (PMID 31856871, 2019). "The protooncogene c-MYC (MYC) regulates the expression of nearly 15% of the human genome and is upregulated in 50% of human cancers." (PMID 31108873, 2019). "An increased MYC copy number and PVT1 expression occur in more than 98% of cancer cases with increased 8q24 copy numbers, which points to an interaction between PVT1 and MYC and that they are part of a common signaling pathway." (PMID 31309249, 2019). "The m6A mRNA methyltransferase METTL3 is upregulated in multiple types of cancers and can promote the m6A modification and expression of oncogenes including EGFR, TAZ, MYC, and SOX2." (PMID 30796352, 2019). "Consistent with the oncogenic role of PVT1 in other cancers, its knockdown reduced proliferation and induced apoptosis in AML cell lines and was accompanied by MYC downregulation in some." (PMID 31338324, 2019). "Findings from this study support that CD105 plays a functional role in maintaining cancer stem cell and EMT phenotype, with MYC as a common mediator for both of these traits." (PMID 31015843, 2019). "Understanding the complexity of MYC-mediated metabolic rewiring in cancers, along with the ways in which MYC cooperates with other signaling drivers such as the mTORC1 and RAS/ERK pathways, can provide translational prospects for cancer therapy." (PMID 31108873, 2019). "The transcription factor MYC, regulating both CC-M4 and PFC-M2, is a cell growth regulator which strongly oncogenic, and estimated to contribute to most cancers." (PMID 31649562, 2019). "This identified ATF4, FOXO1, HIF1A, MAF, MYC, and SREBP1 in FGFR-dependent cancer cells whereas ATF4 and MYC in EGFR-addicted cancer cells, which were required for the transcription of the signature genes in glycolysis or SSP." (PMID 31221965, 2019). "The expressions of MYC, PDIA3, and ITGA5B1 have been demonstrated to play critical roles in various malignant tumors and are independent prognostic factors in certain cancers." (PMID 31886273, 2019). "Like SIRT1, SIRT6 is also able to reduce the transcription of MYC and HIF-1 in cancer cells by reprogramming glucose metabolism." (PMID 30761005, 2019). "Along with MYC and PVT1, the CCDC26 lncRNA gene lies in the human chromosome 8q21 region that is frequently amplified in cancer." (PMID 31338324, 2019).
cancer (continued). "Previous studies have demonstrated that transcription factors such as MYC, SLUG, and SOX2 are responsible for tumorigenesis and can reprogram cells from a differentiated to a stem-like state in a variety of cancers." (PMID 30688660, 2019). "For example, oncogenes including MYC, KRAS, and CCND1 showed strong CES with increasing copy numbers, corroborating the recent studies about cancer dependency on these gene amplifications." (PMID 31732481, 2019). "MYC activity has also been shown recently to be influenced by its interaction with EPIC1, a long non‐coding RNA, that is upregulated in many cancers." (PMID 31304632, 2019). "We previously identified a transcriptional target of MYC, termed BAG1, which is frequently overexpressed in human cancer and predictive of poor prognosis." (PMID 30902071, 2019). "Although physiological HIF1 can inhibit the activity of normal MYC, the altered expression of the oncogenic MYC collaborates with HIF to confer the propensity to cancer cells to convert glucose to lactate, even in the presence of adequate O2 levels." (PMID 31341534, 2019). "Therefore, MYC may be a key regulator for immune checkpoint expression in cancer." (PMID 31824865, 2019). "In humans, genetic alterations in BPTF have been reported in several types of cancer and a role of BPTF in transcriptional regulation by c-MYC has been demonstrated, in agreement with its chromatin-binding function." (PMID 31498079, 2019). "Compared with MYC, relatively little is known about the biological function of ITGA5B1 in carcinoma." (PMID 31886273, 2019). "Increased MYC activity has been previously identified across multiple cancer types, including KRASG12D-driven tumors where MYC has been shown to enhance disease progression." (PMID 30013058, 2018). "Active in DAOY and D283med MB cancer stem cells Active in HD-MB03 cell line and xenograft model Efficiently reduced the metabolic activity in MYC-MB cells." (PMID 30560106, 2018). "Our findings, which demonstrate the ability of an orally available CLK inhibitor to effectively target MYC‐driven cancers, address a novel biological interaction of CLK inhibition with MYC activation." (PMID 29769258, 2018). "In numerous studies in vivo and in vitro, the emerging cancer-related mRNAs have been found, including PTEN, ACTB, MAPK4, MKI67, c-MYC, and CD44." (PMID 29954406, 2018). "Additional peaks involving important cancer genes such as SOX2, MYC, VEGFA and CDK6 were also found." (PMID 29370817, 2018). "c-MYC, NOXA and BAK promote cell death in response to an extended exposure to bortezomib in a number of cancer types." (PMID 29755650, 2018). "To address this question, we first investigated the cellular responses to MYC overexpression (MYCOV ER) in the imaginal wing disc, a Drosophila epithelial tissue widely used to model development, cell competition and cancer." (PMID 30619451, 2018). "MYC, CDK6, PRKACA, and ERBB2 genes were found to frequently interact with other cancer-related genes." (PMID 29716549, 2018). "The estimated IC50 was 4.6 nM, lower than in the MYC/BCL2 DHL cell lines tested in this study (Su-DHL-10, 8.5 nM; Nu-DHL-1, >10.0 nM) and than in a panel of various cancer cell lines reported previously (11–37 nM)." (PMID 30323893, 2018). "(A) Frequency of MYC and FAM84B copy number amplification in 35 cancer types from the TCGA bioportal database." (PMID 30526553, 2018). "c‐MYC and the SWI/SNF chromatin remodeling complex act as master regulators of transcription, and play a key role in human cancer." (PMID 30222246, 2018). "One additional direct transcriptional regulation was found between MYC and CBX5 proteins, but only in “cancer” K562 network." (PMID 29370181, 2018).
cancer (continued). "The three most frequently gained loci in the whole data set were HNF4A in 803 or 47% of 1699 cancers, KLF5 (709 or 42%) and MYC (585 or 34%), all of which have previously been implicated as amplification targets in CRC8,13,14." (PMID 30202008, 2018). "Moreover quantitative genomic alterations can be characteristic of certain cancers like the amplification of the super-enhancer MYCN (myelocytomatosis oncogene of neuroblastoma), a member of the MYC superfamily and of the 450 Ma old MYC interactom, driving most notably high risk neuroblastomas." (PMID 30171420, 2018). "Both c-MYC and MET are proto-oncogenes related to several cancer hallmarks, like sustaining proliferative signaling, evading growth suppressors, enabling replicative immortality and activating invasion and metastasis." (PMID 30143666, 2018). "Peaks involving important cancer genes such as CCND1, EGFR, ERBB2, FGFR1, AKT1, MYC, KRAS and CDKN2A/2B, which were confirmed in our data." (PMID 30131072, 2018). "Interaction of the two bHLH transcription factors MYC and MAX is another well described PPI model to be targeted in cancer." (PMID 29921764, 2018). "To gain insights into the potential role of DNA loop structures in gene control at the MYC locus, we generated cohesin HiChIP data for HCT-116 cells and collected published DNA interaction data for three other cancer cell types for comparison." (PMID 29641996, 2018). "Deregulated expression of MYC is recognized as the Achilles heel of many cancer types and hence is widely regarded to be a promising therapeutic target; however, effective pharmacological MYC inhibitors are elusive, even leading to the conclusion that MYC might be ‘undruggable’." (PMID 30453475, 2018). "Specifically, MYC, CDK6, PRKACA, and ERBB2, all well-known oncogenes and cancer markers, were overexpressed in conjunction with LYL1 gene amplification." (PMID 29716549, 2018). "Driver lncRNA PVT1 was amplified in 18.8% of pan cancers, and gain of PVT1 was required for by stabilizing MYC protein." (PMID 30216655, 2018). "A Cancer Stem Cell Transcription Factor Activation Array (Signosis, Inc, number FA-1004) also found KLF4, MYC, NANOG, OCT-3/4, SOX-2 and SNAIL activated in both MCF-7 and T47D after treatment with the CM of HA-BrC cells (data not shown)." (PMID 29928478, 2018). "In our mouse model of NSCLC [SPC-c-MYC and SPC-C-RAF BxB/SPC-c-MYC], we consistently observed cystic lesions along with malignant lung tumors that have metastasized to liver and other distant organs." (PMID 29464089, 2018). "The expression of miR-34a was then analysed, because this miRNA has a cross talk expression regulation with c-MYC and NOTCH1 and is often down-regulated in cancer stem cells." (PMID 30218041, 2018). "Therefore, the PERK-mediated UPR could be an attractive therapeutic target in MYC-driven cancers." (PMID 29581853, 2018). "OCT4, SOX2, NANOG, Krüppel-like factor 4 (KLF4) and c-MYC play a significant role in triggering pluripotency in somatic cells, and they have been used to identify CSC subpopulations within various types of cancer." (PMID 30177970, 2018). "CCND1 (FC 2.59), BCL2L1 (FC 2.25), MYC (FC 3.70), along with CCND2 (FC 1.60) and SOCS7 (FC 1.51), are all located downstream of STAT activation and were upregulated in carcinoma tissue." (PMID 30603058, 2018). "High MYC amplification was seen in grade III carcinomas (MYC: CEP8 = 2.42), pre-menopausal women (MYC: CEP8 = 2.49), PR-negative status (MYC: CEP8 = 2.42), and ER-positive status (MYC: CEP8 = 2.4)." (PMID 29523126, 2018). "Constitutive activation of NF-κB signaling also leads to upregulation of other transcription factors such as MYC, MAD and ETS-2, and genes such as IL-6 and BMI-1, and inducing resistance to chemotherapy and radiation and proliferating cancer." (PMID 28740573, 2017).
cancer (continued). "The hybrid metabolism phenotype can be stabilized by increased HIF-1 activity, high oncogene (MYC, RAS, c-SRC) activity and high mitochondria ROS production in cancer cells compared with that in normal cells." (PMID 28640191, 2017). "The mTOR pathway is one of the most dysregulated signaling pathways in human cancer, leading to accelerated glucose metabolism by regulating HIF-1α and MYC." (PMID 28337200, 2017). "Induction of MYC-mediated CC in different experimental models and genetic backgrounds may thus represent an invaluable tool to characterise the local and systemic consequences of apoptotic cell death in cancer development, from initiation to unrestrained growth and metastasis." (PMID 28420161, 2017). "Aberrant activation of EGFR, HER2, c-MYC, or MET is considered to be a promising target for specific molecular treatments in various cancers, including CRC." (PMID 28764718, 2017). "MYC is involved in regulating many metabolic enzymes, such as LDHA and HK2 for glycolysis, in cancer cells." (PMID 28474697, 2017). "A third major phenotype induced by inhibition of CDK4/6 in our cancer cell models is a limited response to hypoxia accompanied with downregulation of HIF‐1α, which can also be explained by the accumulation of MYC." (PMID 28978620, 2017). "Lin-28B overexpression increased the expression of the HMGA2, c-MYC and KRAS genes, which are targeted by the cancer suppressor miRNA let-7." (PMID 28947981, 2017). "By contrast, the methyl donor S-adenosylmethionine has been shown to downregulate the oncogenes c-MYC and HRAS, inhibiting cancer cell growth." (PMID 29125844, 2017). "Of these, 22 genes were classified as transcription factors in MSigDB and 15 genes were found in the COSMIC Cancer Gene Census, including ERBB2 (Colo678), MYC (SW480), PPFIBP1 (IS1), and RAD21 (HT29)." (PMID 28683746, 2017). "MYC and PRC2 cooperate not only in ESCs, but also during tumorigenesis; however, the role of PRC2 in cancer is more complex, as its function depends on the tissue context." (PMID 28505071, 2017). "For example, miR‐148a, miR‐34b/c, and miR‐9 downregulate oncogenes, including c‐MYC, E2F3, CDK6, and TGIF2 and are often reduced in cancers." (PMID 28179359, 2017). "Our research laboratory and the laboratory of Bruno Amati demonstrated a direct connection between MYC and CDK2 in modulating cellular senescence in normal cells and cancer cells." (PMID 28665315, 2017). "Transcriptional control of key players of cancer and AR signaling by KDM3A such as KLK3, NKX3-1, MYC were validated by chromatin immunoprecipitation coupled with quantitative real time polymerase chain reaction (ChIP-qRT-PCR)." (PMID 28416760, 2017). "In view of the fact that c-MYC is a crucial regulator of CSCs and SFN possesses the capability in suppressing CSCs in pancreatic and breast cancers, we investigated functional impact of the SFN/miR-214/c-MYC pathway on CSCs in NSCLC." (PMID 28076844, 2017). "These genes belong to relevant intracellular signaling pathways in cancer such as PI3K-Akt (COL4A2, MYC, PDGFA, SPP1), proteoglycans (HIF1A, MYC, PLAUR, TGFB1), and Hippo (CTGF, MYC, NF2, TGFB1)." (PMID 29075357, 2017). "Methylated BAF155 (the core subunit of SWI/SNF complexes) can also be recruited to the MYC target gene GADD45A and promote cancer progression." (PMID 28212646, 2017). "Because PVT1 is less abundant in across normal tissue and possesses a protective role for MYC protein, PVT1 appears to be a promising target for 8q24 amplified cancers." (PMID 29113413, 2017). "Our rationale for choosing these modules as relevant to the KRAS pathway in cancer was as follows: it has been demonstrated that MYC integrates RAS and PI3K signals and that both under- and overexpression of MYC can lead to cancer cell death." (PMID 28152508, 2017).